ESRP1 (epithelial splicing regulatory protein 1)
Diseases named in the same sentence as ESRP1 in open-access papers (continued):
Sharing a sentence is not in itself a finding about the gene and the disease.
orofacial cleft (3 papers, 2020 to 2025). A disorder of facial skeleton that is characterized by cleft lip and/or cleft palate that result in feeding, speech and hearing problems caused by failures during development. "ESRP2 genetic variants in humans are associated with orofacial clefts, and Esrp1 and Esrp1/2 knockout mice display a bilateral cleft of the lip, primary and secondary palate." (PMID 33234718, 2020). "To examine whether there is another stronger candidate in the individual that explains the cleft palate, we examined the 418 previously known genes associated with orofacial cleft, plus the ESRP1 gene in this individual." (PMID 41111330, 2025). "Our finding of anterior pituitary dysmorphogenesis in Esrp1/2 null mice and zebrafish, which also display cleft of the lip and palate, supports an etiological link between orofacial clefts and congenital hypopituitarism that has been previously proposed." (PMID 41111330, 2025). "This work highlights the relative strengths of the mouse and zebrafish models for investigating the morphogenetic mechanisms of orofacial clefts, and contributes new insights into the function of Irf6 and Esrp1/2 during palatogenesis." (PMID 33234718, 2020). "Here, we characterize the Esrp1/2 null mouse, exhibiting bilateral CL/P, as an important model for studying orofacial cleft etiopathogenesis." (PMID 33234718, 2020). "We show that IRF6 and ESRP1 are conserved in their requirement for ANC morphogenesis, where disruption results in orofacial cleft in human, mouse and zebrafish." (PMID 33234718, 2020).
prostate adenocarcinoma (3 papers, 2019 to 2023). "High ESRP2 expression was not prognostic of disease progression in the TCGA (PRostate ADenocarcinoma) PRAD cohort analysed using KM-express, but high expression of ESRP1 associated with a significantly reduced time to first biochemical recurrence (p=0.022)." (PMID 31478829, 2019). "In the publicly available prostate adenocarcinoma dataset, ESRP1 expression was significantly higher in the tumor samples compared to the normal samples (p < 0.001)." (PMID 33194621, 2020). "Accordingly, we sought to determine the clinical implications of ESRP1 mRNA expression using the publicly available prostate adenocarcinoma (PRAD) dataset from The Cancer Genome Atlas (TCGA)." (PMID 33194621, 2020). "RNAseq data from general (i.e. not EOPC) primary prostate adenocarcinomas available in The Cancer Genome Atlas (TCGA) show that high ESRP1 (but not ESRP2) gene expression levels correlate with poorer patient prognosis." (PMID 37752235, 2023).
prostate tumours (3 papers, 2019 to 2023). "Supporting this, Gene Set Enrichment Analysis (GSEA) of gene expression patterns in 250 primary prostate tumours with high levels of ESRP1 in the TCGA PRAD cohort revealed positive enrichment for gene sets associated with DNA replication and mitotic activity." (PMID 37752235, 2023). "ESRP1 and ESRP2 are encoded by genes that are important within the epithelial cells from which prostate tumours are derived, and then play an important role in subsequent tumour development." (PMID 37752235, 2023). "RNA-seq data from prostate tumours show that ADT reduces expression levels of both ESRP1 and ESRP2 genes." (PMID 37752235, 2023). "Immunohistochemistry of ~19,000 prostate tumours correlated high levels of ESRP1 and ESRP2 protein expression with more rapid biochemical tumour recurrence, higher Gleason scores, higher tumour stages and increased numbers of lymph node metastases." (PMID 37752235, 2023). "Why might primary prostate tumours express high levels of ESRP1 and ESRP2 as a strategy to increase tumour growth?" (PMID 37752235, 2023). "Most prostate tumours originate within the prostatic glandular cells and basal cells of the prostate gland, that have been identified from single RNAseq data to have high levels of ESRP1 gene expression." (PMID 37752235, 2023). "What could be the selective advantage for more aggressive prostate tumours to express higher levels of ESRP1 and ESRP2?" (PMID 37752235, 2023). "ESRP2 and its paralog ESRP1 are highly expressed in primary prostate tumours." (PMID 31478829, 2019). "ESRP1 expression levels also decreased in prostate tumours following ADT so might also be under androgen-control in tissue, although did not reciprocally increase following androgen stimulation of cultured cells." (PMID 31478829, 2019). "ESRP1 and ESRP2 both activate splicing of NUMB exon 3, and splicing of this exon in prostate tumours correlates with a reduced time until biochemical tumour recurrence in patients." (PMID 37752235, 2023). "The fact that prostate tumours originate from epithelial cells that already express ESRP1 and ESRP2, and then the ESRP1 and ESRP2 genes subsequently become important within a disease context, fits with the definition of a specific group of oncogenes called lineage-survival oncogenes." (PMID 37752235, 2023). "Since ESRP1 and ESRP2 are over-expressed in aggressive prostate tumours, could they also be targeted to reduce the growth of primary prostate tumours?" (PMID 37752235, 2023). "Potential future therapies could be designed to target ESRP1 and ESRP2 protein activity or their regulated splice isoforms in aggressive prostate tumours." (PMID 37752235, 2023). "We also used these same samples to assess if the observed up-regulation of ESRP1 and ESRP2 could result from prostate tumours consisting of a more pure population of epithelial-derived cells compared to matched tissue." (PMID 31478829, 2019). "Thus, ESRP1 and ESRP2 expression could also be indirectly activated via androgen-regulation of the ERG transcription factor in prostate tumours containing the TMPRS22-ERG genetic fusion." (PMID 37752235, 2023). "Hence, by expressing higher levels of ESRP1 and ESRP2, more aggressive primary prostate tumours may maintain an epithelial gene expression environment to result in a growth advantage." (PMID 37752235, 2023).
small cell lung carcinoma (3 papers, 2021 to 2025). Small cell lung cancer (SCLC) is a highly aggressive malignant neoplasm, accounting for 10-15% of lung cancer cases, characterized byrapid growth, and early metastasis. "ESRP1 suppression induces the formation of the CARM1FL isoform, a full-length transcript of coactivator-associated arginine methyltransferase 1 (CARM1) regulated by ESRP1, giving rise to cisplatin-resistance in small cell lung cancer (SCLC) cells." (PMID 40282556, 2025). "Consistent with the role of ESRP1 in EMT and stemness, ESRP1 overexpression increased the sensitivity of small-cell lung cancer cells to chemotherapy by regulating alternative splicing of CARM1, thereby inhibiting TGF-β/Smad signaling." (PMID 38110955, 2023). "ESRP1 overexpression induced cell apoptosis and cell cycle arrest in small-cell lung cancer cells." (PMID 38110955, 2023). "However, the role of ESRP1 and its mechanism in small cell lung cancer (SCLC) chemoresistance remains unclear." (PMID 33495408, 2021).
viral infection (3 papers, 2016 to 2025). "One notable exception is the transcript encoded by ESRP1 which seemed significantly over-expressed following viral infection (32-fold increase)." (PMID 27598998, 2016). "How the altered expression dynamics of ESRP1 (and other splicing regulators) contribute to AS homeostasis during virus infection remains to be investigated." (PMID 27598998, 2016). "While HFKs express both ESRP1 and isoform 3, they are not considered a likely MCC precursor because viral genes are not expressed following viral infection." (PMID 40407323, 2025).
adenoma (2 papers, 2017 to 2019). A neoplasm arising from the epithelium. "Furthermore, ESRP1 expression is gradually lost during the adenoma to carcinoma sequence in CRC, and loss of ESRP1 protein expression in CRC tumors negatively correlates with patient survival." (PMID 28975893, 2017). "Furthermore, our results from a CRC cohort show that ESRP1 protein is gradually downregulated during the adenoma to carcinoma sequence in intestinal tumors and that few cells express it in lymph node metastases." (PMID 28975893, 2017). "Remarkably, ESRP1 appears to be involved early during CRC tumorigenesis, since it is already downregulated in adenoma." (PMID 28975893, 2017).
cleft palate (2 papers, 2024 to 2025). Cleft palate is a fissure type embryopathy that affects the soft and hard palate to varying degrees. "Notably, ESRP1 germline KO in mice results in a severe cleft palate phenotype leading to neonatal death." (PMID 38815867, 2024).
esophageal cancer (2 papers, 2011 to 2022). A primary or metastatic malignant neoplasm involving the esophagus. "Conceivably, expression of standard CD44 is dependent on loss of ESRP1 and 2 in esophageal carcinoma." (PMID 22069487, 2011).
hearing loss (2 papers, 2022 to 2023). "Since FGF signaling is implicated in various stages of cochlear development, the identification of ESRP1 mutations in a patient with congenital hearing loss naturally led one group of researchers to hypothesize that ESRP1-mediated splicing of FGFRs is essential for hearing." (PMID 36936679, 2023).
Hypertension (2 papers, 2016 to 2023). The presence of chronic increased pressure in the systemic arterial system. "We determined that disruption of an Esrp1‐directed epithelial splicing program is associated with several abnormalities in renal organogenesis that likely have relevance to human congenital kidney diseases that result in childhood or adult‐onset CKD and/or hypertension." (PMID 27404344, 2016).
lung fibrosis (2 papers, 2018 to 2020). "Here, we identified that the pulmonary fibrosis inducer bleomycin simultaneously increased the expression of bFGF and TGF-β1 and inhibited epithelial-specific regulatory protein (ESRP1) expression in vivo and in vitro." (PMID 31868203, 2020). "We have shown that significant differences in the expression of ESRP1, TGF-β1 and bFGF were indicated in bleomycin-induced pulmonary fibrosis, and apparent EMT signs were detected in siESRP1 cells that were treated with TGF-β1, bFGF and bleomycin." (PMID 31868203, 2020). "Taken together, these findings suggest that bleomycin induced EMT through down-regulating ESRP1 by simultaneously increasing bFGF and TGF-β1 in pulmonary fibrosis." (PMID 31868203, 2020). "In addition, our previous study shows that BLM inhibited ESRP1 expression, resulting in enhanced alternative splicing of FGFR2 to the mesenchymal isoform IIIc, thereby induces EMT in the lung fibrosis." (PMID 31868203, 2020).
metastatic tumor (2 papers, 2017 to 2021). "Alternative splicing of CD44 mRNA regulated by epithelial splicing regulatory protein 1 (ESRP1) induces CD44v8-10 expression in metastatic tumor-initiating cells." (PMID 33401672, 2021).
pancreatic adenocarcinoma (2 papers, 2020 to 2021). "ESRP1 knockdown promoted migration and invasion of tumor cells in a model for pancreatic adenocarcinoma." (PMID 33339518, 2020).
triple-negative breast carcinoma (2 papers, 2023). An invasive breast carcinoma which is negative for expression of estrogen receptor (ER), progesterone receptor (PR), and human epidermal growth factor receptor 2 (HER2). "Vascular endothelial growth factor (VEGF)/neuropilin-2 (NRP2)/GLI family zinc finger 1 (GLI1) signaling suppressed ESRP1 expression via transcription repressor polycomb complex protein BMI1 in triple-negative breast cancer cell lines." (PMID 38110955, 2023). "Furthermore, a recent study revealed that ESRP1 overexpression in paclitaxel-resistant population of triple-negative breast cancer cells increases their sensitivity to paclitaxel by regulating α6 integrin splicing." (PMID 38110955, 2023). "CDK5 mediates stemness in triple-negative breast cancer (TNBC) by phosphorylating Peroxisome proliferator-activated receptor gamma (PPARγ) at S273, which curbs its E3 ligase activity and releases epithelial splicing regulatory protein 1 (ESRP1)." (PMID 37993880, 2023).
Apert syndrome (1 paper, 2014). Apert syndrome (AS) is a frequent form of acrocephalosyndactyly, a group of inherited congenital malformation disorders, characterized by craniosynostosis, midface hypoplasia, and finger and toe anomalies and/or syndactyly. "We observed increased expression of Fgf10, Esrp1, and Fgfr2IIIb, which are indispensable for epidermal development, in coronal sutures in Apert syndrome mice." (PMID 25003957, 2014).
basal cell carcinoma (1 paper, 2022). A carcinoma involving the basal cells. "The results suggested that the upregulated genes in ESRP1-low cell lines were highly enriched for terms and pathways such as basal cell carcinoma, negative regulation of epithelial cell differentiation, and extracellular matrix organization." (PMID 36307405, 2022).
breast invasive carcinoma (1 paper, 2021). "Furthermore, the Kaplan–Meier survival analysis using the TCGA breast invasive carcinoma database revealed that a higher expression of ESRP1 is associated with unfavorable patient outcomes." (PMID 34362878, 2021).
colorectal adenoma (1 paper, 2021). An adenoma that arises from the colon or rectum. "Our results also show that aberrant splicing of CD44 occurs in both biologically distinct subtypes of colorectal adenoma possibly in ESRP-1 specific manner." (PMID 34257584, 2021).
COVID-19 (1 paper, 2024). A disease caused by infection with severe acute respiratory syndrome coronavirus 2. "Although there is no reported connection to COVID-19, altered expression of key spliceosome components, including ESRP1, has been mentioned in relation to miR-4454, a microRNA associated with insulin resistance in obesity, as well as with caspase-independent cell death." (PMID 38474155, 2024).
Crohn disease (1 paper, 2017). A gastrointestinal disorder characterized by chronic inflammation involving all layers of the intestinal wall, noncaseating granulomas affecting the intestinal wall and regional lymph nodes, and transmural fibrosis. "To address the general relevance of the findings from our in vitro and in vivo studies, we next assessed ESRP1 expression in intestinal biopsies from Crohn’s disease (CD) patients, after normalization to an epithelial-specific marker." (PMID 28975893, 2017). "(A) ESRP1 transcript levels were measured in inflamed versus matched, non-inflamed intestinal biopsies from Crohn’s disease (CD) patients and normalized to EPCAM expression." (PMID 28975893, 2017).
cutaneous malignant melanoma (1 paper, 2020). "However, the expression and regulatory network of ESRP1 in cutaneous malignant melanoma (CMM) remain unclear." (PMID 32964032, 2020). "However, the specific role of ESRP1 in cutaneous melanoma remains unclear." (PMID 32964032, 2020).
cystic fibrosis (1 paper, 2025). Autosomal recessive disorder caused by pathogenic variants in the CFTR gene (cystic fibrosis transmembrane conductance regulator), which encodes a chloride and bicarbonate channel expressed in epithelial cells, and follow the diagnosis criteria. "Importantly, ESRP1 is markedly elevated in the livers of patients with BA and cystic fibrosis-related liver disease, localizing to cholangiocytes and peri-biliary hepatic cells, but is minimal in primary sclerosing cholangitis and primary biliary cholangitis." (PMID 41594551, 2025).
endometrial cancer (1 paper, 2022). Primary or metastatic malignant neoplasm involving the endometrium (mucous membrane that lines the endometrial cavity). "Indeed, our data suggest that its loss may significantly mitigate disease risk by reducing the expression of several proteins (ESRP1 and DHRS2) with known deleterious effects in endometrial cancer in addition to modulating cell viability and proliferative capacity." (PMID 35401936, 2022).
gallbladder cancer (1 paper, 2019). "As the levels of the mRNA of ESRP1 is down-regulated, the CD44 variant isoform is replaced by the CD44 standard isoform which promotes EMT, increasing invasiveness in gallbladder cancer." (PMID 31552163, 2019).
hypopituitarism (1 paper, 2025). A condition of diminution or cessation of secretion of one or more hormones from the anterior pituitary gland. "The discovery of this key function for Esrp1/2 in pituitary formation has significant fundamental and clinical implications for understanding congenital hypopituitarism and craniofacial anomalies." (PMID 41111330, 2025).
inflammatory bowel disease (1 paper, 2017). A spectrum of small and large bowel inflammatory diseases of unknown etiology. "In humans, ESRP1 is downregulated in inflamed biopsies from inflammatory bowel disease patients." (PMID 28975893, 2017).
intestinal tumors (1 paper, 2017). "Representative IHC showing ESRP1-high and -low intestinal tumors." (PMID 28975893, 2017).
invasive carcinoma (1 paper, 2016). A carcinoma that is not confined to the epithelium, and has spread to the surrounding stroma. "Furthermore, ESRP1 was found to be more strongly expressed in the nucleus of normal colon epithelium cells compared to adjacent invasive carcinoma cells of 2/3rds of the tumor tissues with low transcript expression in T compared to N tissue." (PMID 27650542, 2016).
kidney cancer (1 paper, 2013). Primary or metastatic malignant neoplasm involving the kidney. "Moreover, ESRP1 is also highly expressed in CD133+ human kidney progenitor cells, but downregulated in kidney cancer stem cells (protein extracts kindly provided by B. Bussolati)." (PMID 24015231, 2013).
oral cancer (1 paper, 2022). "OVOL1/2 transcriptional factors can impress ZEB-1 transcriptional factors associated with EMTvia a feedback loop and regulate the splicing of mRNA via epithelial splicing regulatory protein 1 (ESRP1) induction in oral cancer." (PMID 36146567, 2022).
ovarian serous adenocarcinoma (1 paper, 2017). An adenocarcinoma that arises from the ovary and is characterized by the presence of malignant epithelial cells that, in well differentiated tumors, resemble the epithelium of the fallopian tube or, in poorly differentiated tumors, show anaplastic features and marked nuclear atypia. "Of the 69 cases of ovarian serous adenocarcinomas examined for ESRP1, 53 (76.8%) cases showed moderate or strong expression with higher expression than normal ovaries (left)." (PMID 28991261, 2017).
ovarian serous cystadenocarcinoma (1 paper, 2017). A malignant serous cystic epithelial neoplasm arising from the ovary. "Accordingly, using TCGA data, we analyzed the association of ESRP1 expression with clinical outcome in patients with ovarian serous cystadenocarcinoma (n=541)." (PMID 28991261, 2017). "TCGA data revealed that ESRP1 gene expression is significantly higher in primary ovarian serous cystadenocarcinoma (n=541) than normal ovarian tissues (n=4; P=0.003)." (PMID 28991261, 2017).
periodontitis (1 paper, 2021). An acute or chronic inflammatory process that affects the tissues that surround and support the teeth. "ISG20 and ESRP1 were found to be highly correlated with immunocyte infiltration, immune signaling activation, and HLA expressions in periodontitis." (PMID 34285922, 2021). "The strong associations among ISG20, ESRP1 and activated B cell, BCR signaling pathway, and HLA-DOB in periodontitis were first identified in our study." (PMID 34285922, 2021). "Paired with the immune characteristics above, the most strongly correlated RBPs were ISG20 and ESRP1, suggesting that ISG20 and ESRP1 might have potent impact on the immune microenvironment in periodontitis." (PMID 34285922, 2021). "Our study depicted the correlations among RBPs and immune microenvironment and biological reactions in periodontitis, with strong correlations of the RBPs ISG20 and ESRP1 with activated B cell infiltration, BCR signaling activation, and HLA-DOB expression." (PMID 34285922, 2021).